PUS1 (pseudouridine synthase 1)
Description:
Pseudouridylate synthase that catalyzes pseudouridylation of tRNAs and mRNAs. Acts on positions 27/28 in the anticodon stem and also positions 34 and 36 in the anticodon of an intron containing tRNA. Also catalyzes pseudouridylation of mRNAs: mediates pseudouridylation of mRNAs with the consensus sequence 5'-UGUAG-3'. Acts as a regulator of pre-mRNA splicing by mediating pseudouridylation of pre-mRNAs at locations associated with alternatively spliced regions. Pseudouridylation of pre-mRNAs near splice sites directly regulates mRNA splicing and mRNA 3'-end processing. Involved in regulation of nuclear receptor activity through pseudouridylation of SRA1 mRNA.
Synonyms: MLASA1
Tractability: Small molecule: a structure with a bound ligand is known. PROTAC: ubiquitination databases record sites on it; its protein half-life has been measured.
Target class: Isomerase; Enzyme
Gene: Protein-coding gene on chromosome 12 (131,929,200 to 131,945,896, forward strand). Ensembl gene ENSG00000177192.
Subcellular location: Mitochondrion (Isoform 1); Nucleus (Isoform 2); Cytoplasm
Subcellular location (Human Protein Atlas): Mitochondria; Nucleoplasm
Pathways (Reactome):
Metabolism of RNA: tRNA modification in the mitochondrion; tRNA modification in the nucleus and cytosol
Gene Ontology:
Molecular function: mitochondrial tRNA pseudouridine(27/28) synthase activity; pseudouridine synthase activity; RNA binding; steroid receptor RNA activator RNA binding; tRNA binding; tRNA pseudouridine synthase activity; chromatin binding; transcription coactivator activity; tRNA pseudouridine(38-40) synthase activity
Biological process: mRNA pseudouridine synthesis; tRNA pseudouridine synthesis; mitochondrial tRNA pseudouridine synthesis; positive regulation of DNA-templated transcription; pseudouridine synthesis; RNA modification
Cellular component: cytoplasm; mitochondrion; nucleoplasm; nucleus; mitochondrial matrix; nuclear lumen; nucleolus; transcription regulator complex
Genetic constraint (gnomAD): Loss-of-function variants: 25 observed, 30.07 expected, observed/expected ratio (o/e) 0.83, 90% interval 0.61 to 1.16. The upper end of that interval is the gene's LOEUF score, 1.16, which puts it in group 5 of 6, group 1 being the genes least tolerant of losing a copy. Missense variants: 597 observed, 561.38 expected, observed/expected ratio (o/e) 1.06, 90% interval 0.99 to 1.14. Synonymous variants: 282 observed, 240.82 expected, observed/expected ratio (o/e) 1.17, 90% interval 1.06 to 1.29.
Gene-disease validity (ClinGen):
ClinGen rates the evidence that PUS1 causes each of these diseases.
mitochondrial disease (autosomal recessive): Definitive.
Homologues: Orthologues: chimpanzee PUS1 (99% identical), macaque PUS1 (95% identical), rat Pus1 (84% identical), pig PUS1 (82% identical), mouse Pus1 (81% identical), guinea pig PUS1 (79% identical), dog PUS1 (77% identical), zebrafish pus1 (55% identical), Drosophila melanogaster Pus1 (41% identical), Caenorhabditis elegans pus-1 (33% identical). Paralogues in human: PUS3 (22% identical), PUSL1 (16% identical).
Diseases named in the same sentence as PUS1 in open-access papers:
PUS1 is named in the same sentence as 49 diseases in open-access papers, as found by Europe PMC text mining. Sharing a sentence is not in itself a finding about the gene and the disease. The quoted sentences say what the papers report.
sideroblastic anemia (12 papers, 2014 to 2025). "MLASA syndrome (myopathy, lactic acidosis and sideroblastic anemia) was first described as associated with PUS1 pathogenic variants, and later in patients with similar phenotype YARS2 pathogenic variants." (PMID 34441767, 2021). "As a further complication of mt-tRNA synthetase dysfunction, the involvement of blood cells has been implicated by mutations in PUS1, resulting in mitochondrial myopathy, lactic acidosis and sideroblastic anaemia (MLASA)." (PMID 24412566, 2014). "To date, six genes have been discovered that may cause sideroblastic anemia: PUS1, YARS2, LARS2, TNRNT1, NDUFB11 and MT-ATP6." (PMID 34441767, 2021). "Sideroblastic anaemia is characterised by the presence of ringed sideroblasts in the bone marrow and can be caused by PUS1 deficiency (affecting mitochondrial pseudouridine synthase) and presenting clinically as myopathy, lactic acidosis and sideroblastic anaemia (MLASA)." (PMID 25778941, 2015). "Second, understanding the biology of Pus1 could shed light on the biology of human PUS1, mutation of which has been associated with the rare autosomal recessive disease mitochondrial myopathy and sideroblastic anemia (MLASA) and the related condition congenital sideroblastic anemia (CSA)." (PMID 39848696, 2025). "In fact, the responsiveness to pyridoxine seen in XLSA also helps to distinguish it from other congenital causes of inherited sideroblastic anemia with mutations in SLC25A38, ABCB7, GLRX5, PUS1, and SLC19A genes." (PMID 39995829, 2024). "Despite its role in various diseases such as myopathy, lactic acidosis and sideroblastic anaemia (MLASA) syndrome where PUS1 gene is mutated, recent studies additionally elucidated the versatile role of PUS1 in cancer." (PMID 37315299, 2023). "In humans, loss of Pus1 function is linked to the disorder MLASA (mitochondrial myopathy with lactic acidosis and sideroblastic anemia), which underscores the general importance of Pus1-dependent Ψ formation." (PMID 32392804, 2020).
lactic acidosis (9 papers, 2011 to 2025). Metabolic acidosis characterized by the accumulation of lactate in the body. "PUS1 deficiency links to mitochondrial myopathy with lactic acidosis via disrupted oxidative phosphorylation." (PMID 41377071, 2025). "Mutations in the PUS1 gene have been linked to mitochondrial myopathy, encephalopathy, lactic acidosis, and stroke-like episodes (MELAS)." (PMID 37701433, 2023). "Numerous researches revealed that aberrant expression of PUS1 was closely linked to lactic acidosis and mitochondrial myopathy." (PMID 36092937, 2022). "YARS2 and PUS1 mutation screening was performed on a cohort of ten French or Italian patients with demonstrated RC enzyme deficiency who also presented with anaemia and at least one of the other MLASA features, ie. lactic acidosis or myopathy." (PMID 24344687, 2013).
Mitochondrial myopathy (9 papers, 2011 to 2025). "Mutation of the pseudouridylate synthase 1 gene (PUS1) was found to cause mitochondrial myopathy and SA." (PMID 21326867, 2011).
hepatocellular carcinoma (7 papers, 2023 to 2025). A malignant tumor that arises from hepatocytes. "The expression of PUS1 is associated with overall survival in hepatocellular carcinoma, and it has been described that RBFOX3 plays a role in the chemosensitivity to 5-Fluorouracil in hepatocellular carcinoma." (PMID 37835382, 2023). "PUS1 knock-down has been shown to inhibit hepatocellular carcinoma (HCC) cell proliferation and tumorigenesis, whereas PUS1 overexpression promotes HCC growth both in vitro and in vivo." (PMID 40260225, 2025). "Depletion of PUS1 and MARS1 has been shown to suppress cancerous phenotypes in hepatocellular carcinoma, renal cell carcinoma, and breast cancer." (PMID 40918643, 2025). "In hepatocellular carcinoma (HCC), a novel prognostic signature composed of 6 key lactate metabolism-related genes (FKTN, PDSS1, PET117, PUS1, RARS1, and RNASEH1) was developed to predict the survival and tumor microenvironment of HCC patients." (PMID 38529390, 2024).
breast carcinoma (5 papers, 2022 to 2026). "Consistently, previous studies in breast cancer and liver cancer have indicated PUS1 as an independent prognosis factor." (PMID 37925171, 2023). "In conclusion, our results suggested the great potential of PUS1 as an unfavorable biomarker for breast cancer." (PMID 36457503, 2022). "An RNA sequencing method was used to explore how PUS1 regulates breast cancer cells’ biological processes, which was then validated by in vitro experiments." (PMID 36457503, 2022). "A tissue microarray of 131 breast cancer patients was then utilized to determine the clinical significance and prognostic value of PUS1." (PMID 36457503, 2022). "In this study, we screened the expressions of pseudouridine synthase family members in breast cancer by an integrative analysis and choose PUS1 as the candidate biomarkers for this tumor." (PMID 36457503, 2022). "In line with the PUS1 level in breast cancer tissues, PUS1 were highly expressed in most TNBC cell lines compared with the normal mammary epithelial cell and other tumor cell lines." (PMID 36457503, 2022). "In current study, we examined the aberrant expression of PUS1 in breast cancer as well as its clinical significance and prognostic value." (PMID 36457503, 2022). "In order to determine the clinical significance of aberrant PUS1 expression in breast cancer, we evaluated PUS1 expression by immunohistochemistry in tissue microarrays from 131 patients." (PMID 36457503, 2022). "Our first step in analyzing PUS1’s phenotypic impact on breast cancer is to assess the relative protein level of PUS1 in breast cancer cells." (PMID 36457503, 2022). "This evidence suggested that knocking down PUS1 decreased breast cancer cells’ ability to invade, which was consistent with our bioinformatic analysis of the RNA sequencing data." (PMID 36457503, 2022). "Based on our enrichment analysis, we propose a possible mechanism for PUS1 in promoting breast cancer progression." (PMID 36457503, 2022). "According to our findings, breast cancer tissues showed a greater expression of PUS1 than normal tissues." (PMID 36457503, 2022). "Studies have shown that PUS1 is a prognostic factor in liver cancer and breast cancer." (PMID 37925171, 2023). "Breast cancer tissues showed high PUS1 mRNA and protein expression as compared to normal tissues." (PMID 36457503, 2022). "Our results suggested that PUS1 is a novel biomarker that predicts poor outcomes in patients with breast cancer and may prove to be a promising treatment target." (PMID 36457503, 2022). "Moreover, the molecular mechanisms of PUS1 involvement in melanoma and breast cancer, and PUS10 involvement in prostate cancer have also been initially explored." (PMID 36437949, 2022). "As high expression of PUS1 correlates with poor prognosis, we hypothesize that PUS1 is a tumor-promoting gene in breast cancer." (PMID 36457503, 2022). "Then we tested whether PUS1 knockdown affected breast cancer cells’ long-term survival capacity, and the number of colonies formed by tumor cells was also significantly diminished at low PUS1 levels." (PMID 36457503, 2022). "PUS1 might be a promising treatment target for breast cancer." (PMID 36457503, 2022). "The mRNA levels of key PUS family members, i.e., PUS1, PUS3, PUS4, and PUS7, were significantly higher in breast cancer patient tissues compared with normal breast tissues." (PMID 41554761, 2026). "While higher expression of PUS4 was associated with more favorable prognosis, higher expression of PUS1, PUS3, and PUS7 in breast cancer patients was correlated with poorer prognosis." (PMID 41554761, 2026). "The elevated expression of PUS1, RPUSD2, and MARS in breast cancer cases showed a positive correlation with high Ki67 levels (FC: 1.35, 1.04, and 1.41, respectively), suggesting their contributing role in tumor growth." (PMID 40918643, 2025). "Therefore, it is possible that PUS1 could serve as a future therapeutic target for breast cancer." (PMID 36457503, 2022).
breast carcinoma (continued). "We also found that positive correlation between high PUS1 expression and unfavorable pathological parameters including higher tumor grade and TNBC status, which represent the higher degrees of malignancy and more aggressive biological behavior of breast cancer." (PMID 36457503, 2022). "Third, this study sought to investigate whether PUS1 has clinical significance in breast cancer as well as how it affects phenotypic features of cells, but the direct RNA substrates of PUS1 as well as the complicated roles of pseudouridylation modifications on breast cancer has not been explained." (PMID 36457503, 2022).
renal cell carcinoma (5 papers, 2023 to 2026). "Pseudouridine (Ψ) modification is a prevalent epitranscriptomic mark with critical roles in carcinogenesis; however, the function of its catalytic "writer" enzyme, pseudouridine synthase 1 (PUS1), in renal cell carcinoma (RCC) remains elusive." (PMID 42003926, 2026). "High PUS1 expression is closely associated with renal cell carcinoma (RCC)." (PMID 38476632, 2024). "PUS1 silencing can significantly inhibit the proliferation and invasion of breast tumors and may serve as a potential diagnostic biomarker for various cancers, including renal cell carcinoma (RCC)." (PMID 41501031, 2026).
prostate carcinoma (3 papers, 2022 to 2025). A carcinoma that arises from epithelial cells of the prostate gland. "To gain deeper insights into the importance of PUS1 in regulating EIF3b and promoting prostate cancer cell bone metastasis, we integrated data from the TCGA database on PUS1 mutations in prostate cancer." (PMID 39247811, 2024). "This study uncovers a novel regulatory mechanism of the FOXA1/PUS1/EIF3b signaling axis in prostate cancer bone metastasis." (PMID 39247811, 2024). "In summary, our study confirms that PUS1 interacts with EIF3b, suppressing TTC3-mediated ubiquitination degradation, thereby identifying PUS1 as a novel protective molecule of EIF3b, mediating prostate cancer metastasis both in vitro and in vivo." (PMID 39247811, 2024). "In summary, our data demonstrate that Mogroside IV-E inhibits PUS1 expression in a dose-dependent manner and suppresses both in vitro and in vivo metastasis of prostate cancer cells." (PMID 39247811, 2024). "Transcriptomic scrutiny of PUS1 expression across six prostate cancer in situ foci, including six foci with bone metastases, unveiled heightened PUS1 levels in the latter." (PMID 39247811, 2024). "Given the important role of EIF3b in prostate cancer 24, 25, we focused on the contribution of EIF3b to PUS1-mediated prostate cancer metastasis." (PMID 39247811, 2024). "We also identified a small-molecule inhibitor of PUS1, Mogroside IV-E, which dose-dependently inhibits prostate cancer bone metastasis." (PMID 39247811, 2024). "We identified elevated PUS1 expression in prostate cancer tissues, correlating with higher clinical grade and worse prognosis." (PMID 39247811, 2024). "To elucidate the degradation pathway of EIF3b, we employed inhibitors targeting these pathways, namely the ubiquitin-proteasome pathway inhibitor MG132 and the autophagy inhibitor bafilomycin (Baf), in PUS1-knockdown prostate cancer cells." (PMID 39247811, 2024). "Subsequent analysis revealed that only FOXA1, a potential regulator of PUS1, was significantly upregulated in prostate cancer tissues." (PMID 39247811, 2024). "In this study, we present the novel finding that pseudouridine synthase PUS1 is overexpressed in prostate cancer tissues and is positively correlated with adverse patient outcomes for the first time." (PMID 39247811, 2024). "Our findings highlight the FOXA1/PUS1/EIF3b axis as a critical mediator of prostate cancer bone metastasis and suggest that targeting this pathway could be a promising therapeutic strategy." (PMID 39247811, 2024). "Intriguingly, within tumor specimens, PUS1 expression positively correlated with tumor grade, stage, and poor prognosis, providing compelling insights into its clinical relevance and prognostic potential in prostate cancer." (PMID 39247811, 2024). "Furthermore, targeting PUS1 with Mogroside IV-E offers a new therapeutic approach and means for the prevention and treatment of prostate cancer bone metastasis." (PMID 39247811, 2024). "Overall, our data suggest that the FOXA1/PUS1/EIF3b signaling axis may serve as an effective therapeutic target for treating prostate cancer bone metastasis." (PMID 39247811, 2024). "In various prostate cancer cell lines (such as 22RV1, C4-2, DU145, LNCaP, and PC-3), as well as benign prostate hyperplasia cell line RWPE-1, we examined PUS1 expression using qPCR and Western blot." (PMID 39247811, 2024). "Both wild-type and mutant PUS1 significantly enhanced tumor cell migration compared to controls, and the RNA pseudouridylation levels in the mutant group were similar to controls, indicating that PUS1 primarily functions through a non-enzymatic pathway in prostate cancer cells." (PMID 39247811, 2024). "Mechanistically, PUS1 exerts a non-enzymatic function by directly binding to and stabilizing EIF3b, protecting it from TTC3-mediated ubiquitination and degradation, thereby promoting prostate cancer metastasis." (PMID 39247811, 2024).
breast tumors (2 papers, 2022 to 2023). "Consistent with their results showing that silencing of PUS1 significantly suppressed breast tumor proliferation and invasion, our data further made a complement for PUS1 function in tumor, providing with evidence that PUS1 would be a potential diagnose marker for cancers, including RCC." (PMID 37315299, 2023). "We found that breast tumors overexpressed PUS1 compared with paired normal tissues." (PMID 36457503, 2022).
colorectal cancer (2 papers, 2023 to 2025). A primary or metastatic malignant neoplasm that affects the colon or rectum. "Consistent with findings in breast and colorectal cancer, we observed increased expression of PUS1, MARS, and RPUSD2 in the SCAN-B cohort." (PMID 40918643, 2025).
glioma (2 papers, 2021 to 2024). A benign or malignant brain and spinal cord tumor that arises from glial cells (astrocytes, oligodendrocytes, ependymal cells). "Six Ψ synthase genes were associated with the prognosis, of which the expression of PUS1, PUS7, RPUSD1 and RPUSD3 was positively associated with the malignancy of glioma (HR > 1), and TRUB1 was negatively associated with the malignant grade (HR < 1)." (PMID 35118063, 2021). "The results showed that PUS1, PUS7, and DKC1 were significantly correlated with the prognosis of gliomas in different subgroups." (PMID 35118063, 2021).
liver cancer (2 papers, 2023 to 2025). An epithelial or non-epithelial malignant neoplasm that arises from the liver. "Therefore, PUS1 is highly expressed in liver cancer patients and may be a novel diagnostic biomarker." (PMID 40171259, 2025).
lung carcinoma (2 papers, 2023 to 2024). "The expression of PUS1 in lung cancer and its matched adjacent normal tissues of patients from GSE101929, GSE87340, GSE40419, and GSE75037 confirmed the results." (PMID 37925171, 2023). "In lung cancer (LUAD, LUSC), DKC1, PUS1, PUS3, PUS7, TRUB1, and TRUB2 expression was mostly negatively correlated with immune cell infiltration." (PMID 39162904, 2024).
ovarian carcinoma (2 papers, 2021 to 2023). A malignant neoplasm originating from the surface ovarian epithelium. "Further analysis indicated that PUS7 may interact with NOC3L and PUS1 to regulate ovarian cancer proliferation via modulation of DNA replication and the cell cycle." (PMID 34827123, 2021).